BCL2 (BCL2 apoptosis regulator)
Diseases named in the same sentence as BCL2 in open-access papers (continued):
Sharing a sentence is not in itself a finding about the gene and the disease.
ulcer (9 papers, 2019 to 2025). "The observed reduction in p63, Ki67 and bcl-2 levels predisposes to epithelial thinning, erosions and/or ulcers." (PMID 40138076, 2025). "The observed combination of simultaneous reduction in p63, Ki67 and bcl-2 levels predisposes to epithelial thinning, erosions and/or ulcers." (PMID 40138076, 2025). "Mechanistically, evidence indicates that ethanol intake down-regulates the anti-apoptosis gene Bcl-2, an effect markedly driven by the accumulation of oxygen-derived free radicals and pro-inflammatory signals in the area of the ulcer area." (PMID 40283949, 2025). "Compared to the ulcer group, the Cls and Omp groups had a significant reduction in gastric cleaved caspase-3 content and a significant rise in gastric Bcl-2 content." (PMID 38884677, 2024). "The gene expression of Bcl-2 was reduced, while Bax gene expression was elevated in the ulcer group when related to control animals." (PMID 36432009, 2022). "Results showed that the gene expression of Bcl-2 was reduced, whereas Bax gene expression and caspase-3 and 9 were both elevated in the ulcer group." (PMID 36432009, 2022). "The present results describe an imbalance of apoptotic proteins in ethanol positive ulcer group; with an upregulation of proapoptotic protein; Bax; and downregulation of antiapoptotic protein; Bcl-2; with a subsequent increase in Bax/Bcl-2 ratio as compared to the negative control." (PMID 31404064, 2019). "By reducing the expression of pro-apoptotic proteins like BAX and increasing anti-apoptotic proteins like BCL-2, HDZJF likely helps to prevent cell death in the oral mucosa, promoting tissue regeneration and reducing ulcer severity." (PMID 40129983, 2025). "Pretreatment with PdGs or OMZ significantly downregulated Bax and Casp3 mRNA expression, and upregulated Bcl2 expression, suggesting that PdGs and OMZ suppressed gastric ulceration by inhibiting apoptosis." (PMID 31194753, 2019).
ZIKV infection (9 papers, 2019 to 2024). "For example, a Zika virus infection was found to induce AKI by activating apoptosis through suppressing Bcl-2 expression." (PMID 39359936, 2024). "To gain insight into the mechanism of apoptotic induction after ZIKV infection, we performed an immunofluorescence analysis on Bcl2." (PMID 38139100, 2023). "ZIKV infection suppressed Bcl-2 expression and induced excessive inflammatory responses by activating the NLRP3 inflammasome, which subsequently led to kidney injury shown by impaired glomerular filtration and tubular re-absorption ability." (PMID 31474993, 2019). "In summary, our findings illustrated the mechanism of ZIKV infection induced AKI through activating NLRP3 inflammasome via suppressing Bcl-2." (PMID 31474993, 2019). "Furthermore, ZIKV infection induced a decreased expression of B-cell lymphoma-2 (Bcl-2) in the kidney." (PMID 31474993, 2019). "Therefore, our work identified a novel role of ZIKV infection in inducing AKI by activating NLRP3 inflammasome via suppressing Bcl-2." (PMID 31474993, 2019). "Since Bcl-2 attenuated the activation of NLRP3 inflammasome and apoptosis of renal cells, we further confirm whether Bcl-2 reduced renal cell injury induced by ZIKV infection." (PMID 31474993, 2019). "ZIKV infection reduced the expression level of Bcl-2 in HK-2 cells, whereas cells transfected with Bcl-2 plasmid significantly enhanced Bcl-2 expression in both mock or ZIKV-infected HK-2 cells, which confirmed the efficiency of the protocol of Bcl-2 overexpression." (PMID 31474993, 2019). "Upon ZIKV infection, we observed an increase of Bcl-2 at the protein level." (PMID 31671831, 2019). "Based on the fact that Bcl-2 family protein was involved in ZIKV infection with a Bcl-2 protein level quantitatively maintained, we formulated the hypothesis that ZIKV might allow a stabilization of the Bcl-2 protein over time and inhibit MOMP formation." (PMID 31671831, 2019). "We performed a western blot assay to measure Bcl-2 protein level upon ZIKV infection." (PMID 31671831, 2019). "In addition, ZIKV-infected microglia downregulated anti-apoptotic gene BCL2 expression, indicating that ZIKV infection may promote glial cell apoptosis." (PMID 32843067, 2020). "A previous study showed the importance of Bcl-xL for cells survival, in deficient Bcl-2 cells during ZIKV infection, but here we could not exclude a role for Bcl-2 and/or Bcl-xL protein as our model expressed these two anti-apoptotic proteins." (PMID 31671831, 2019). "This induction also regulated the expression of Bcl2 and NUMB, mimicking the effect observed in ZIKV infection." (PMID 39347716, 2024). "More importantly, Bcl-2 played a negative role in both ZIKV infection-induced NLRP3 inflammasome activation and apoptosis by down-regulating the NLRP3 priming and the expression of pro-apoptotic proteins, respectively." (PMID 31474993, 2019). "Moreover, the expression of miR34c reduces NSCs and GSCs cell growth and regulates both Bcl2 and NUMB expression, mimicking the same effect observed in the ZIKV infection." (PMID 30890698, 2019). "Even though the role of Bcl-2 in NLRP1 inflammasome activation mechanism is well-appreciated, it's still unknown whether Bcl-2 is involved in regulating NLRP3 inflammasome activation induced by ZIKV infection." (PMID 31474993, 2019).
astrocytoma (8 papers, 2002 to 2024). "In astrocytomas, a significantly higher percentage of cells expressing Bcl-xL protein compared to Bcl-2 protein was found, whereas a reverse trend was observed in oligodendrogliomas." (PMID 32260403, 2020). "The unique expression of CHOP in HIV-1 gp120 clade C and Bcl-2 in HIV-1 gp120 clade B reaffirm that HIV-1 gp120 proteins exert a clade dependent specific response in cell death through UPR activation in U87 astrocytoma cells." (PMID 28978127, 2017). "Moreover, following HIV-1 gp120 clade B treatment, the expression level of the ER-stress suppressor of apoptosis Bcl-2 protein was significantly increased in astrocytoma." (PMID 28978127, 2017). "However, whether HSP10 influences apoptosis via Raf signaling cascade or Bcl-2/Bax pathway or others in astrocytoma is continually needed to be further verified." (PMID 29028811, 2017).
cutaneous melanoma (8 papers, 2008 to 2025). A primary melanoma arising from atypical melanocytes in the skin. "In human cutaneous melanoma, evasion of apoptosis occurs through upregulation of BCL2 and/or loss of APAF-1." (PMID 34822659, 2021). "In fact, Bcl-2 has been shown highly expressed in virtually all cutaneous melanomas and Bcl-2 overexpression has been reported to be associated with an unfavorable outcome in cutaneous melanomas." (PMID 23443086, 2012). "Our study revealed that DIOS significantly suppressed the proliferation and migration of cutaneous melanoma cells, reduced the levels of Bcl-2, and increased the protein expressions of Cleaved caspase-9, Cleaved caspase-3, and Cleaved PARP." (PMID 39844566, 2025). "The MITF also positively regulates the expression of Bcl2, an anti-apoptotic factor, in normal melanocytes and human cutaneous melanoma cells." (PMID 39000342, 2024). "The role of bcl-2, a proto-oncogene that inhibits apoptosis, has been studied in several malignancies, including cutaneous melanoma (CM)." (PMID 18570663, 2008). "After correcting for multiple testing, the only significant promoters were TERT in cutaneous melanoma and pan-cancer; BCL7A, IGLL5, BCL2, and POLR3E pan-cancer; and HNRNPR in uterine adenocarcinoma." (PMID 36396655, 2022).
diabetic retinopathy (8 papers, 2019 to 2024). "Down-regulates caspase-3, caspase-9 and Bax expression; up-regulates Bcl-2 expression; and possibly plays a protective role in diabetic retinopathy by reducing oxidative stress induced by high glucose and inhibiting cell damage and apoptosis." (PMID 35566359, 2022). "Recent studies have reported that 2ME prevents apoptosis by increasing the expression of Bcl-2 in kidney IR injury and by inhibiting the expression of caspase-3 in animal models of diabetic retinopathy and global ischemia." (PMID 33796096, 2021). "Intraocular PACAP injection attenuates proapoptotic signals (p-p38MAPK and caspase-3, -8 and -12) and promotes anti-apoptotic factors (p-Akt, p-ERK1, p-ERK2, PKC and Bcl-2) in experimental diabetic retinopathy." (PMID 33466261, 2021). "MiR-21 is broadly related to metabolic disorders, e.g., CVD, diabetic retinopathy, kidney fibrosis, atherosclerotic plaques, and β-cell apoptosis, and it has been shown to influence Bcl-2 in type 1 diabetes in vivo models." (PMID 32962281, 2020). "The anti-inflammatory role of miR-204 has been recently elucidated in rats with diabetic retinopathy where the effect was likely mediated through Bcl-2 and SIRT1 upregulation, thus providing insight into another potential mechanistic pathway underlying this condition." (PMID 39488562, 2024). "In addition, analysis of TUNEL and apoptosis-related indicators (cleaved caspase 3 and BAX/Bcl-2 ratios) further confirmed that pancreatic kallikrein could improve apoptosis in diabetic retinopathy." (PMID 30838453, 2019). "Another miRNA, miR-195, was upregulated in the course of diabetic retinopathy leading to aggravated OxS, mitochondrial damage and apoptosis of RPE cells via Bcl-2 targeting." (PMID 32962281, 2020). "The levels of Bcl-2 and SIRT1 could be upregulated by miR-204 to inhibit inflammation and apoptosis in diabetic retinopathy rats." (PMID 37819496, 2023).
intervertebral disc degeneration (8 papers, 2014 to 2024). "The imbalance of Bax and Bcl-2 level induced C-caspase-3 expression and caused NP cells apoptosis, which are related to the mitochondrial apoptosis pathway during intervertebral disc degeneration." (PMID 38019477, 2023). "Tetrahedral nucleic acids loaded with microRNA155 can alleviate intervertebral disc degeneration in rats and inhibit nucleus pulposus cell apoptosis via Bcl‐2/Bax apoptosis pathway." (PMID 38899529, 2024). "Epigenetic silencing of miRNA-143 regulates apoptosis by targeting BCL2 in human intervertebral disc degeneration." (PMID 30704538, 2019). "Overexpression of antiapoptotic proteins through the mitochondrial pathway (e.g., Bcl-2) may represent a specific, effective molecular treatment option in degenerative disc disease." (PMID 25763091, 2015). "Taken together, overexpression of antiapoptotic proteins through the mitochondrial pathway (for example, Bcl-2) may represent a specific, effective molecular treatment option in degenerative disc disease." (PMID 24472667, 2014).
Lymphadenopathy (8 papers, 2007 to 2023). Enlargement (swelling) of a lymph node. "While Bcl2-Tg mice developed lymphadenopathy and died around 50 weeks, Bcl2-Tg/Tfl-/- mice lost body weight around 30 weeks and died about 20 weeks earlier than Bcl2-Tg mice." (PMID 37304286, 2023). "It has been previously published that patients with lymphadenopathy with an LN size bigger than 50 mm receiving targeted therapies (BTK of BCL2 inhibitors) have a worse progression-free survival (PFS) compared to those with LNs of smaller dimensions." (PMID 35683596, 2022). "In fact, BCL2(Tg)/lpr-transgenic mice exhibit substantially enhanced lymphadenopathy compared with lpr or BCL2(Tg) only mice, which is mainly explained by the enhanced accumulation of both immature double negative (CD4−/CD8−) and double positive (CD4+/CD8+) T-cells." (PMID 27206675, 2016). "Mice treated with empty liposomes had severe splenomegaly (1405±133 mg, n = 7) and lymphadenopathy, similar to untreated TRAF2DN/Bcl-2 mice with overt disease." (PMID 17593960, 2007). "In contrast, mouse littermates representing all the other genotypes (TRAF3-/BCL2-; TRAF3+/BCL2-, and TRAF3-/BCL2+) did not develop significant lymphadenopathy or clonal B cell expansions within the observation period of 20 months." (PMID 30687320, 2018).
lymphoproliferative disorders (8 papers, 2010 to 2024). "In contrast, immunohistochemical analysis of BCL2 protein expression is a simple, well-validated, inexpensive and widely available test (used routinely in diagnostic pathology of low-grade lymphoproliferative disorders)." (PMID 20664598, 2010). "In addition, it would certainly be interesting to investigate the effects of ABT‐199/venetoclax, a more specific inhibitor of BCL‐2, in combination with rituximab or cyclophosphamide in BCL‐2 positive lymphoproliferative disorders associated with EBV." (PMID 32623836, 2020). "The diverse patterns of BCL2 deregulation are thus likely impacting the phenotype of BCL2-driven lymphoproliferative disorders." (PMID 36358756, 2022). "Our findings underline the probable pathogenic role of BCL2 in LyP and the potential therapeutic efficacy of venetoclax for the treatment of this primary cutaneous CD30+ lymphoproliferative disorder, especially in the setting of severe and refractory disease." (PMID 34568060, 2021). "EBV latent membrane protein 1 is an attractive hypothesis as it up-regulates bcl-2, which has been shown to confer a survival advantage for lymphocytes in other lymphoproliferative disorders, and thus could enhance tissue lymphocyte accumulation and survival in LIP." (PMID 25896166, 2015). "Overexpression of BCL‐2 has been found, for example, in LCL and type III BL cell lines, as well as in EBV‐positive lymphoproliferative disorders harboring type III latency, including PTLD." (PMID 32623836, 2020). "In these lymphoproliferative disorders, EBV infection induces an increase in the expression of the anti‐apoptotic protein BCL‐2." (PMID 32623836, 2020). "We designated these mice BCL2+IL6+AID− and found that they developed—with full genetic penetrance (100% incidence) and suitably short latency (93 days median survival)—a severe IgM+ lymphoproliferative disorder that recapitulated important features of human WM." (PMID 27813533, 2016). "None of the Bcl-2+ patients had history of other lymphoproliferative disorders." (PMID 26475474, 2015).
neuroendocrine tumors (8 papers, 2003 to 2025). "While activated MAPK signaling suppresses neuroendocrine lineage differentiation, concomitant overexpression of MYC or BCL2 accelerates neuroendocrine tumor formation." (PMID 39456595, 2024). "The present paper describes a case of SPC with bcl-2 expression, which is known as a marker for malignancy of neuroendocrine tumors." (PMID 28105053, 2016). "However, the tumor cells showed positive reactivity for bcl-2, which is a poor prognostic indicator of neuroendocrine tumors." (PMID 28105053, 2016). "Interestingly, despite bcl-2 expression being a poor prognostic indicator of neuroendocrine tumors, the patient with this tumor has achieved long-term survival (approximately 6 years) at the time of writing this report." (PMID 28105053, 2016). "Overall, Bcl-2 protein was expressed in 39% of the lung tumours studied: 71% in SCLC, 55% in neuroendocrine tumours and 35% in NSCLC." (PMID 12838300, 2003). "Consequently, further studies are necessary to determine the value of Bcl-2 as a prognostic factor for survival in SCLC and in neuroendocrine tumours." (PMID 12838300, 2003). "Therefore, we suggested that bcl-2 expression also reflexes the good prognosis of the patients with SPC rather than prognostic indicators in several kinds of neuroendocrine tumor." (PMID 28105053, 2016).
pneumonia (8 papers, 2016 to 2025). An acute, acute and chronic, or chronic inflammation focally or diffusely affecting the lung parenchyma, caused by an infection in one or both of the lungs (by bacteria, viruses, fungi, or mycoplasma.). "The findings of the present study revealed that in the animal model of pneumonia, the level of BCL-2 was significantly reduced, while other apoptotic markers including BAX, CASP-3, and CASP-9 were remarkably increased." (PMID 38580929, 2024). "The remaining four patients with migrating pneumonia had received either anti-BCMA agents or venetoclax, a B-cell lymphoma-2 (Bcl-2) inhibitor, all of which have been associated with diminished immune responses to SARS-CoV-2 vaccines, suggesting impaired immune responses to the virus." (PMID 40283531, 2025). "Bcl-2 antagonists, such as venetoclax, have shown in a recent phase II clinical trial in refractory CLL an incidence of pneumonia in 6% and febrile neutropenia in 5% of patients." (PMID 27597852, 2016). "Interestingly, the present results showed that EGCG, through the modulation of BCL-2, BAX, CASP-3, and CASP-9, prevented pneumonia-induced apoptosis." (PMID 38580929, 2024).
renal fibrosis (8 papers, 2016 to 2025). A final common manifestation of a wide variety of chronic kidney diseases characterized by glomerulosclerosis and tubulointerstitial fibrosis. "The findings suggest that TGF-β1 and Bcl-2 are associated with renal fibrosis and apoptosis in feline kidney cells." (PMID 39858257, 2025). "This study concludes that TGF-β1 and Bcl-2 may be associated with renal fibrosis and apoptosis in feline kidney cells." (PMID 39858257, 2025). "This suggests that the Bax/Bcl-2 ratio may be significant and that it likely affects caspase-3 in mediating the apoptosis linked to inflammation and renal cell loss throughout the development of renal fibrosis." (PMID 36547838, 2023). "In the nephrotoxic nephritis (NTN) kidneys, the ratio of Bax to Bcl-2 at protein levels was consistently elevated in the ALCL3-treated group and exhibited strong correlations with caspase-3 activity, apoptosis, inflammation, and renal fibrosis." (PMID 36547838, 2023).
rheumatoid arthritis (8 papers, 2013 to 2024). A chronic, systemic autoimmune disorder characterized by inflammation in the synovial membranes and articular surfaces. "Trx1 overexpression has also been associated with Bcl2 expression and decreased apoptosis in fibroblasts of rheumatoid arthritis patients." (PMID 36837907, 2023). "Likewise, liquiritin also targeted the MAPK pathway in rheumatoid arthritis (RA) by downregulating the B-cell lymphoma-2 (Bcl-2)/Bcl-2-associated X (Bax) ratio, c-Jun N-terminal kinase (JNK), and p38 phosphorylation, as well as VEGF expression." (PMID 35082907, 2022). "Increased BCL-2 expression in the synovial fibroblasts is documented in the RA (rheumatoid arthritis) synovial membrane where it contributes to inflammation and is more pronounced than in OA synovial fibroblasts." (PMID 33540799, 2021).